MIR3910-1 (microRNA 3910-1)
Synonyms: hsa-mir-3910-1; mir-3910-1
Gene: MicroRNA gene on chromosome 9 (91,636,251 to 91,636,361, forward strand). Ensembl gene ENSG00000266855.
Diseases named in the same sentence as MIR3910-1 in open-access papers:
MIR3910-1 is named in the same sentence as 1 disease in open-access papers, as found by Europe PMC text mining. Sharing a sentence is not in itself a finding about the gene and the disease.
MIR3910-1 shares sentences with these, for which no sentence is quoted: autism (1 paper).